PIWIL2 (piwi like RNA-mediated gene silencing 2)
Diseases named in the same sentence as PIWIL2 in open-access papers (continued):
Sharing a sentence is not in itself a finding about the gene and the disease.
tumor (52 papers, 2007 to 2025). "Low PIWIL2 expression is associated with higher T stage, significantly correlating with other pathological features, such as vascular and perineural invasion, tumor stage, or lymph node involvement, leading to tumor aggressiveness." (PMID 38031146, 2023). "Our previous researches had showed that PIWIL2 plays roles in tumorigenesis and tumor development through several underlying mechanisms." (PMID 33469229, 2021). "We investigated the expression pattern and possible association of PIWIL-2 with epithelial stem cell compartments and neoplasias." (PMID 32166374, 2020). "Significantly, PIWIL2 has been linked to age, size of the tumor, histological type, tumor stage and lymph node metastasis." (PMID 32211149, 2020). "PIWIL-2 expression has been shown to be associated with stem cell properties and has been regarded as a potential neoplasia biomarker." (PMID 32166374, 2020). "In the tumor group showing PIWIL2 underexpression, significant positive associations were observed with PR- status (p = 0.0025), ERBB2 negative status (p = 0.039) and molecular subtype (p = 0.004)." (PMID 33008024, 2020). "For this, we analyzed protein expression in complete resected tumor samples, and found a significant association between PIWIL2 expression and both progression-free and overall survival (p = 0.036 and p = 0.012, respectively)." (PMID 31443431, 2019). "Our previous study showed that PIWIL2 plays roles in tumorigenesis and tumor development through several underlying mechanisms." (PMID 29555935, 2018). "While full length PIWIL2 can mediate DNA repair acting as a barrier gene to the initiation of tumorigenesis and promote apoptotic cell death in tumor tissues, its variants such as PL2L60 and PL2L60A can promote tumorigenesis." (PMID 28545024, 2017). "Piwil2 promotes proliferation and inhibits apoptosis in tumor cells; however, the underlying mechanisms remain largely unclear." (PMID 27602489, 2016). "As c-Myc is a transcription factor (TF) located in nucleus in tumor cells, here we also detected the alteration of c-Myc caused by PIWIL2 expression by immunofluorescence (IF)." (PMID 25193865, 2014). "Especially, we have found that PIWIL2 expression is associated with the development of tumor stem cell (TSCs)." (PMID 22110608, 2011). "The Piwil2 expression was also significantly higher in BC than in para-cancerous tissues and hyperplasias, and its protein expression rate was associated with age, histological type, tumour stage and size, and lymph node metastasis." (PMID 33807045, 2021). "Therefore, by suppressing apoptosis and inducing autophagy, PIWIL2 plays roles in the survival of tumor cells and associates with poor prognosis in ESCC patients." (PMID 33469229, 2021). "Interestingly, the expression of PIWIL2 protein in tumor samples had a statistically significant association with progression-free survival (p = 0.036)." (PMID 31443431, 2019). "In contrast, PIWIL2 variants PL2L proteins, such as PL2L60, were detected abundantly in various types of tumor tissues and tumor cell lines, suggesting that the tumorigenic functions of PIWIL2 might be mediated mainly by PIWIL2 variants." (PMID 28545024, 2017). "Interestingly, PIWIL2 gene can be alternatively activated in tumor cells by intragenic promoters, resulting in a number of Piwil2 variants, namely Piwil2-like (PL2L) proteins with a potential function in tumorigenesis." (PMID 22110608, 2011). "Recently we and others have found that Piwil2 may play important roles in tumor development, despite the fact that the underlying mechanisms are not yet clear." (PMID 22110608, 2011). "Recently, we have reported that ectopic expression of germline stem cell gene PIWIL2 is associated with tumor stem cell development, although the underlying mechanisms are largely unknown." (PMID 22110608, 2011). "Among PIWI subfamily members, PIWIL2 might play unique roles in tumor development, although the underlying mechanisms are largely unknown." (PMID 20975993, 2010).
tumor (continued). "Furthermore, lower PIWIL2 expression exhibited a trend toward significance with other pathologic characteristics associated to tumor aggressiveness such as vascular invasion (p = 0.068), neural invasion (p = 0.108), tumor stage (p = 0.111), or lymph nodes involved (p = 0.128)." (PMID 31443431, 2019). "Recent studies have demonstrated that PIWIL2 is expressed in various tumors.Our previous studies together with others’ also indicate that PIWIL2 contributes to proliferation and antiapoptosis in tumor cells, however, the underlying mechanisms remain largely unclear." (PMID 25193865, 2014). "This further denotes PIWIL2 as the member of the pathway that is potentially most critical for tumor initiation." (PMID 40789164, 2025). "Along these lines, both our CRISPR/Cas9-generated PIWIL2 KO cells, as well as our PIWIL2 knockdown cells using a shRNA, exhibit slower proliferation rate, compared to the control cells, which would imply a tumor-promoting role for PIWIL2." (PMID 40789164, 2025). "To disrupt these interactions, we designed novel decoy peptides that potentially competes with both HDAC3 and NME2, effectively inhibiting PIWIL2-driven tumor activity in Huh7, HepG2, SNU449, and SNU398 HCC cell lines." (PMID 41422314, 2025). "PIWIL2 interacts with Siah2, activating this pathway, which in turn promotes tumor growth and metastasis." (PMID 39596284, 2024). "High tumour staining for each of HMGA2, MUC5AC/6, IDH1, PIWIL2, DNA index, and RPL34 was significantly associated with poorer OS upon multivariable analysis." (PMID 38398089, 2024). "In vivo experiments using mouse xenograft models supported the in vitro findings, showing that DEX-induced tumor growth and metastasis are mediated by PIWIL2 signaling." (PMID 39596284, 2024). "Knockdown of PIWIL2 decreased the proliferation, tumorigenic, and chemoresistant capacity of CC cells, while overexpression of PIWIL2 activated tumor-initiating capabilities and upregulated several cell reprogramming factors." (PMID 38328436, 2023). "In HPV-infected cervical epithelium, the oncoproteins E6 and E7 activate PIWIL2, which then reprogram the cells that initiate tumor-initiating cells (TICs) and tumorigenesis of the cervix." (PMID 38031146, 2023). "In particular, it was found that PIWIL2 expression was associated with the Gleason score and the TNM (Tumour Node Metastasis) stage." (PMID 35204687, 2022). "In contrast, downregulated expression of PIWIL1, PIWIL2, and PIWIL4 genes was observed in high-stage RCC tumour samples and was associated with worse overall survival (OS) of patients." (PMID 35204687, 2022). "Piwil2 plays an important role in the transformation of cervical epithelial cells to tumor-initiating cells by epigenetic regulation." (PMID 34295823, 2021). "Our results revealed that mice injected with PIWIL2 knockdown stable cells showed dramatically decreased tumor volume compared to those injected with wildtype cells (376.5 ± 213.5 mm3 vs 1665.9 ± 275.4 mm3, p = 0.008)." (PMID 33469229, 2021). "This was evident even after operative removal of the primary tumour, and this strongly contrasts with the metastasis noted in only 13% of patients with lower expressed Piwil2." (PMID 33807045, 2021). "In hepatocellular carcinoma, co-expression of Piwil2/Piwil4 has potential as an indicator for tumor prognosis." (PMID 34295823, 2021). "Piwil2 and Piwil4 are highly expressed in SKBR3 cell lines, and altered Piwil2 expression was demonstrated in 30.8% CD44+/CD24- cells cultured from resected tumour tissues." (PMID 33807045, 2021). "PIWIL1 was exclusively observed in the cytoplasm of tumor cells and PIWIL2 was identified in the nucleus." (PMID 33008024, 2020). "PIWIL2 protein expression not only localized on the cytoplasm of tumor cells, but also weakly in the cytoplasm of stroma cells in those cases with high PIWIL2 expression levels." (PMID 31443431, 2019).
tumor (continued). "The Piwil2 gene, expressed in tumor stem cells and germ cells, plays an important role in the self-renewal of stem cells, embryo formation and transcriptional regulation." (PMID 31703718, 2019). "Since The Human Protein Atlas Project only provides PIWIL2 mRNA expression, we described for the first time the protein expression profile of PIWIL2 in human tumor samples by using human testis tissues to determine the best antibody concentration." (PMID 31443431, 2019). "Our previous researches have shown that PIWIL2 promoted tumorigenesis and tumor development through many different ways." (PMID 29555935, 2018). "A single tumor derived from PIWIL2-GFP fibroblast spheroid injected into a nude mouse was used to study gene expression by RT-PCR." (PMID 28103575, 2017). "Reprogramming of fibroblasts with PIWIL2 into ITGCs affords a novel approach to study the molecular mechanisms involved in tumor initiation, maintenance and differentiation." (PMID 28103575, 2017). "In this study, we have cloned and characterized a human intragenic promoter that resides in the intron 10 of the host gene PIWIL2, which is responsible for the transcription of mRNA encoding PL2L60 proteins in testicular cells and tumor cells." (PMID 28545024, 2017). "All tumors displayed GFP fluorescence indicating that the tumor cells were primarily of PIWIL2-GFP transfected human fibroblast origin." (PMID 28103575, 2017). "The Piwil2-iCSC tumor tissue was proved to be an embryonal undifferentiated carcinoma, which supported the effect of Piwil2 on the occurrence and development of tumors." (PMID 27894076, 2017). "In this study we demonstrate that cells with tumor-genic properties can be generated in vitro from human somatic cells by reprogramming with the PIWIL2 gene." (PMID 28103575, 2017). "This new experimental model, based on defined reprogramming with PIWIL2, provides a potential tool for the in vitro study of human tumor initiation and development." (PMID 28103575, 2017). "The differences in the expression and location of Piwil2 and Piwil4 in tumor cells were explored, and the influence of such differences on the long-term survival rate of HCC was studied using Kaplan-Meier survival curve and log-rank test." (PMID 27894076, 2017). "Since the variants such as PL2L60 has opposite functions to full length PIWIL2 in tumor development, e.g., tumor promoting vs. tumor suppression, we have referred to the intragenic promoter-mediated activation as aberrant or alienated activation of host gene." (PMID 28545024, 2017). "While PIWIL2 was down–regulated in our gene expression dataset, hsa_piR_021032 showed up-regulation in the tumor tissues, suggesting a possible repression of the PIWI gene by the piRNA." (PMID 27177224, 2016). "Piwil1 was only detected in the cytoplasm of tumor cells in few cases, while Piwil2 and Piwil4 were detected in most of the cases." (PMID 27329591, 2016). "In contrast, Piwil2 overexpression induced malignant transformation of HaCaT cells and the acquisition of tumor-initiating capabilities." (PMID 27602489, 2016). "PIWIL1 and PIWIL2 mRNAs expression resulted altered in tumor tissues, confirming previous observations in HCC." (PMID 27429044, 2016). "The tumor formation model was performed to demonstrate the effects of PIWIL2 on tumor formation in vivo." (PMID 26373553, 2015). "We found that mice treated with PIWIL2-transfected A549 cells had significantly increased tumor volumes compared to controls." (PMID 26373553, 2015). "PIWIL2 and 4 were downregulated in tumor tissue in comparison to the normal tissue (p < 0.001) and the patients with lower levels of PIWIL4 had shorter TTR (p = 0.048) and OS (p = 0.033)." (PMID 25742785, 2015). "Previous studies demonstrate that PIWIL2 contributes to proliferation and antiapoptosis in tumor cells." (PMID 25193865, 2014). "Taken together, our present work demonstrates that PIWIL2 modulates tumor cell proliferation and F-actin filaments via promoting c-Myc expression." (PMID 25193865, 2014).
tumor (continued). "Additional findings obtained here show that PIWIL2 is a new partner of NME2 in tumor cells, and the role of this interaction in c-Myc transcriptional regulation needs to be further elucidated." (PMID 25193865, 2014). "Deficiency of either PIWIL2 or NME2 protein impairs the c-Myc expression, leading to defects in cell cycle progress and proliferation in tumor cells." (PMID 25193865, 2014). "Our present results revealed that PIWIL2 induces RhoA expression via regulating c-Myc, modulates F-actin filaments and affects tumor cell invasion and migration." (PMID 25193865, 2014). "Taken together, these data suggested that c-Myc plays a part in PIWIL2-regulated tumor cell cycle progress and cell proliferation." (PMID 25193865, 2014). "Our present work provides a novel insight into c-Myc overexpression occurring in tumor cells, and expands the knowledge of PIWIL2 in tumorigenesis." (PMID 25193865, 2014). "In order to validate previous findings of the correlation between tumor differentiation subtype and PIWIL2 short isoforms expression, we used an in vitro cell line model experiment." (PMID 25384072, 2014). "Consistently the same protein bands in the human tumor cell lysates were almost completely blocked by Piwil2 peptides, which were used as immunogens." (PMID 20975993, 2010). "Interestingly, SLC39A14 expression in HCC samples, including AJHCC007, was lower than in non-tumor samples, while PIWIL2 expression was markedly elevated in AJHCC007." (PMID 41422314, 2025). "PIWIL2 depletion in colon epithelial Caco2 cells leads to increased anchorage-independent growth, decreased levels of TE-targeting non-canonical piRNAs, increased LINE-1 levels and activity, and in DNA damage, altogether highlighting a tumor-suppressing role of PIWIL2 in the colon." (PMID 40789164, 2025). "Altogether, the data support the idea that PIWIL2 acts as a tumor suppressor in the colon." (PMID 40789164, 2025). "Interestingly, in this tumor type PIWIL2 expression negatively correlated with the stem cell markers POU5F1 and NANOG." (PMID 38303021, 2024). "Their contribution to tumor progression may be explained by the maintenance of the CSC subpopulation since PIWIL1 and PIWIL2 have been associated with expression of CSC markers and increased tumor formation, migration and invasion." (PMID 38303021, 2024). "Interestingly, while full length PIWIL2 acts as an oncosuppressor via DNA repair, the PL2L60 variant seems to have oncogenic properties in tumor progression." (PMID 33008024, 2020). "Thus, PIWIL2 plays an important role in the transformation of cervical epithelial cells to tumor-initiating cells (TICs) by epigenetic regulation." (PMID 31399034, 2019). "Furthermore, the survival analysis performed with patients stratified by tumor origin revealed the prognosis significance of PIWIL2 expression and its potential value to predict the outcome of patients with tumors that originated in the pancreas." (PMID 31443431, 2019). "As molecular chaperones, Piwil2/Piwil4 are co-expressed and localized in the tumor tissue." (PMID 27894076, 2017). "In addition to gametogenesis, PIWIL2 can promote tumorigenesis through upregulating several signal transduction pathways and inhibiting apoptotic death of tumor cells via activation of Stat3/Bcl-XL pathway." (PMID 28545024, 2017). "Piwil2 is a potent inhibitor apoptosis so it may play an important role in tumor induction, proliferation and survival." (PMID 28103575, 2017). "The co-expression and localization of molecular chaperone Piwil2/Piwil4 in the tumor tissue could be used as an indicator for tumor prognosis." (PMID 27894076, 2017).
tumor (continued). "To further verify the existence of PL2L60 mRNAs (amRNA of PIWIL2), we examined the expression of PL2L60 proteins after knockdown of putative PL2L60 mRNAs in human tumor cell lines, using the siE21 siRNAs, which targeted exon 21 of PIWIL2, PL2L80 and PL2L60 transcripts." (PMID 28545024, 2017). "This bias might partly be explained by the preferential usage of either Piwil1 or Piwil2 in these tumor types as indicated by qPCR." (PMID 27183847, 2016). "Previously, PIWIL2 was shown to be expressed in most tumours as a set of its shorter isoforms." (PMID 25384072, 2014). "Since PIWIL2 could promote tumor cells proliferation, we examined whether PIWIL2 regulates the proliferation trait of tumor cells through c-Myc." (PMID 25193865, 2014). "Notably, similar to the knockdown of RhoA, c-Myc knockdown diminished RhoA expression as well as filamentary F-actin in tumor cells induced by PIWIL2." (PMID 25193865, 2014). "Finally, PIWIL2 knockdown in murine bone marrow mesenchymal stem cells has been shown to enhance cell proliferation and decrease expression of tumor suppressors." (PMID 25384072, 2014). "Due to c-Myc/RhoA pathway being conducive to tumor cell invasion and migration, we first investigate whether PIWIL2 modulates the invasion and migration features of tumor cells by performing Transwell and wound healing assays." (PMID 25193865, 2014). "Together, these results showed that PIWIL2 can upregulate c-Myc expression in tumor cells." (PMID 25193865, 2014). "Besides, when NME2 expression vector was co-transfected with shPIWIL2, the specific band indicating NME2/PIWIL2/G4-motif complex remained undetected, suggesting that interaction between NME2 and G4-motif complex is PIWIL2-dependent in tumor cells." (PMID 25193865, 2014). "Our molecular and functional studies, demonstrated Piwil2 as a key player in the process of tumor initiation, progression and invasion, suggestthat this factor can be used as a common cancerbiomarker, as well as a target for the developmentof new anticancer drug." (PMID 24027667, 2013). "Therefore, Piwil2 canbe used not only as a common biomarker for tumor, but also as a target for the developmentof new anticancer drug." (PMID 24027667, 2013). "These investigations will provide a novel insight into roles of Piwil2 in tumor cells." (PMID 22303479, 2012). "In agreement with the previous report, the primers Pmili, which is specific for exons 18–21 (E18-21) of murine Piwil2 and was routinely used in our laboratory for the detection of “Piwil2” mRNA in pCSCs and other tumor cell lines, reproducibly amplified the “Piwil2” mRNA in the pCSC lines." (PMID 20975993, 2010). "The mechanism(s), how PIWIL2 contributes to tumor progression and maintenance of a stem cell-like phenotype are largely unknown, but a study found that the CpG island in the promoter of Latexin, a negative stem cell regulatory gene, was more frequently methylated in PIWIL2+ breast CSCs." (PMID 38303021, 2024). "Therefore, it could be deduced that the difference in the localization of Piwil2 and Piwil4 in tumor cells could be related to the malignant degree or prognostic phenotype of HCC." (PMID 27894076, 2017). "So we next examined whether PIWIL2 regulates circadian proteins in tumor cells." (PMID 28903391, 2017). "Moreover, transfection of PIWIL2 promoted tumor growth in nude mice." (PMID 26373553, 2015). "Besides, PIWIL2 overexpression resulted in enhanced migration in tumor cells." (PMID 25193865, 2014). "Therefore, the Piwiil2-mediated DNA repair strongly suggests that Piwil2 act as a gatekeeper to genotoxic agents-mediated carcinogenesis and may play a critical role in preventing the initiation and development of a tumor." (PMID 22110608, 2011).